AKT2 (AKT serine/threonine kinase 2)
Diseases named in the same sentence as AKT2 in open-access papers (continued):
Sharing a sentence is not in itself a finding about the gene and the disease.
liver cancer (8 papers, 2017 to 2026). An epithelial or non-epithelial malignant neoplasm that arises from the liver. "AKT1 and AKT2 are widely distributed in the liver, and a recent study demonstrated that AKT1 and AKT2 mice are more susceptible to liver cancer." (PMID 36874613, 2023). "Pharmacological inhibition of β-catenin, AKT2, and/or pyrimidine synthesis abolishes β-catenin mutant liver cancer." (PMID 36122209, 2022). "In the cancer studies, miR-137 was found to exert its anti-tumor activity via inhibiting the AKT2/mTOR signaling pathway in the liver cancer." (PMID 29016699, 2017). "Moreover, AKT2 expression is positively corelated with CTNNB1 expression in human liver cancer samples in The Cancer Genome Atlas (TCGA)." (PMID 36122209, 2022). "We demonstrated that regulation of pyrimidine synthesis by the β-catenin/AKT2 cascade still exists in MEFs, which lacks GS enzymatic activity, in S6K-depleted liver cancer cells, and in Tsc2 null cells where potential activation of β-catenin/AKT2 on S6K is disconnected." (PMID 36122209, 2022). "Notably, AKT2 was described as one mediator of the growth of liver cancer cells by stimulating the expression of PKM215." (PMID 28871187, 2017). "Therefore, targeting AKT2-potentiated pyrimidine synthesis may be a promising therapeutic strategy for β-catenin mutant liver cancer." (PMID 36122209, 2022). "Stimulation of β-catenin/AKT2/CAD signaling cascade on pyrimidine synthesis is an essential and druggable vulnerability for β-catenin mutant liver cancer." (PMID 36122209, 2022). "As a transcriptional activator of AKT2, β-catenin potentiates AKT2 phosphorylation of CAD, which in return stimulates de novo pyrimidine synthesis and liver cancer development." (PMID 36122209, 2022). "Moreover, we identified oncogenic β-catenin–boosted de novo pyrimidine synthesis via stimulation of the AKT2–CAD (carbamoyl-phosphate synthetase 2, aspartate transcarbamoylase, dihydroorotase) signaling pathway in liver cancer development and its clinical significance in cancer treatment." (PMID 36122209, 2022).
non-small cell lung carcinoma (8 papers, 2011 to 2023). A group of at least three distinct histological types of lung cancer, including non-small cell squamous cell carcinoma, adenocarcinoma, and large cell carcinoma. "AKT2 is highly expressed in many human cancers, including non-small cell lung cancer, colorectal cancer, and thyroid cancer." (PMID 35887001, 2022). "AKT2 is highly expressed in many human cancers, including non-small cell lung cancer (NSCLC)." (PMID 32873299, 2020).
osteosarcoma (8 papers, 2011 to 2024). A usually aggressive malignant bone-forming mesenchymal neoplasm, predominantly affecting adolescents and young adults. "In osteosarcoma, AKT2 expression is significantly higher in cancerous tissues than in noncancerous tissues, implying shortened event-free survival and overall survival." (PMID 32873299, 2020). "We demonstrated that AKT2 is a direct target of miR-200c, Spearman’s rank correlation analysis showed that the expression levels of AKT2 and miR-200c in 35 pairs of osteosarcoma specimens were inversely correlated." (PMID 29051585, 2017). "Secondly, AKT2 expression was significantly abolished in osteosarcoma cells which miR-200c stablely-expressed." (PMID 29051585, 2017). "In summary, we have identified a link between miR-200c and AKT2 that is a novel constituent of osteosarcoma tumorigenesis." (PMID 29051585, 2017). "Given that PI3Kα/Akt signaling (specific PI3Kα, Akt1 and Akt2 isoforms) mediate Wnt5a-induced the migration of osteosarcoma cells, we propose that PI3Kα/Akt act as the downstream of Wnt5a and ROR2." (PMID 29213214, 2017). "Then, we determine the correlation between AKT2 levels and miR-200c expression levels in the same osteosarcoma tissues." (PMID 29051585, 2017). "Spearman’s rank correlation analysis showed that the expression levels of AKT2 and miR-200c in 35 pairs of osteosarcoma specimens were inversely correlated (Spearman’s correlation r = −0.6686)." (PMID 29051585, 2017). "Taken together, we demonstrate that RhoA acts as the downstream of PI3K/Akt signaling (specific PI3Kα, Akt1 and Akt2 isoforms) and mediated Wnt5a-induced the migration of osteosarcoma cells." (PMID 28289332, 2017). "In conclusion, RhoA acts as the downstream of PI3K/Akt signaling (specific PI3KαAkt1 and Akt2 isoforms) and mediated Wnt5a-induced the migration of osteosarcoma cells." (PMID 28289332, 2017). "We present the evidence here that RhoA mediates Wnt5a-induced osteosarcoma cell migration via PI3Kα, Akt1 and Akt2 isoforms." (PMID 28289332, 2017). "MiR-200c regulate cell proliferation, cell migration and chemosensitivity to cisplatin in osteosarcoma by targeting AKT2." (PMID 29051585, 2017). "Taken together, the present study provides the first evidence that miR-200c is significant in suppressing osteosarcoma growth through inhibition of AKT2 translation." (PMID 29051585, 2017). "Because Akt3 appears to be predominantly expressed in the brain, we used the specific inhibitors to block PI3Kα, PI3Kβ, PI3Kγ, PI3Kδ, Akt1 and Akt2 activity and studies the effects of each isoform of PI3Ks and Akts in osteosarcoma cell migration in this study." (PMID 28289332, 2017). "In this study, we demonstrated that RhoA activation acts as the downstream of Wnt5a/PI3K/Akt signaling, and is specifically regulated by PI3Kα, Akt1 and Akt2 isoforms in osteosarcoma cells." (PMID 28289332, 2017). "We therefore investigated if knockdown of Akt2 promoted drug-induced apoptosis in cultured osteosarcoma cells in vitro." (PMID 21686164, 2011). "Taken together, for the first time, our results demonstrate that miR-200c plays a significant role in osteosarcoma tumor growth and chemosensitivity by regulating AKT2, which may provide a novel therapeutic strategy for treatment of osteosarcoma." (PMID 29051585, 2017). "Here, PI3Kα, PI3Kβ, Akt1 and Akt2 isoforms regulate Wnt5a-induced osteosarcoma cell migration." (PMID 28289332, 2017). "Thus, AKT2 silencing has become an efficient therapeutic strategy in osteosarcoma, but it is still far from optimal and novel therapeutic strategies are needed urgently." (PMID 29051585, 2017). "Finally, osteosarcoma tissues exihibits higher levels of AKT2 which are inversely correlated with miR-200c expression." (PMID 29051585, 2017). "Furthermore, cell growth rate in the presence of cisplatin (5 μM) was assayed by CCK-8 proliferation assay at different time points, forced expression of AKT2 reversed miR-200c-induced osteosarcoma chemosentivity to cisplatin." (PMID 29051585, 2017).
osteosarcoma (continued). "In this study, we investigated the hypothesis that knockdown of Akt2 plays an important role in osteosarcoma cell chemosensitivity to cisplatin-induced apoptosis through upregulation of PUMA." (PMID 21686164, 2011). "The results of this study suggest that knockdown of Akt2 expression may have therapeutic applications in enhancing the efficacy of chemotherapy in patients with osteosarcoma." (PMID 21686164, 2011). "Furthermore, we measured the mRNA levels of AKT2 in osteosarcoma specimens and normal tissues." (PMID 29051585, 2017).
atherosclerosis (7 papers, 2011 to 2022). A disease characterized by the build-up of fatty material and calcium deposition in the arterial wall resulting in partial or complete occlusion of the arterial lumen. "In both studies, in vitro data supported a role for Akt2 in macrophage migration, inflammation and polarisation, suggesting that Akt2 deficiency reduces atherosclerosis through impaired macrophage function." (PMID 25929188, 2015). "Bone marrow transplantation (BMT) studies demonstrated a very similar protective role of macrophage Akt2 deficiency in atherosclerosis progression." (PMID 25929188, 2015). "Our data demonstrate that loss of Akt2 suppresses the ability of macrophages to undergo M1 polarization reducing both early and advanced atherosclerosis." (PMID 25240046, 2014). "To dissect the impact of macrophage Akt1 and Akt2 on early atherosclerosis, we generated mice with hematopoietic deficiency of Akt1 or Akt2." (PMID 25240046, 2014). "Thus, loss of macrophage Akt2 expression has an isoform-specific impact on the development of atherosclerosis." (PMID 25240046, 2014). "Akt2 deficiency associated with the M2 phenotype can also contribute to atherosclerosis regression." (PMID 25240046, 2014). "However, the impact of macrophage phenotypes generated by Akt1 and Akt2 deficiency on atherosclerosis remains unclear." (PMID 25240046, 2014). "Our results demonstrate a critical isoform-specific role of Akt2 in macrophage polarization and atherogenesis in vivo, thus suggesting new therapeutic targets for the prevention and treatment of atherosclerosis." (PMID 25240046, 2014). "This is the first in vivo demonstration that M2 polarization of macrophages achieved through genetic alteration of Akt2 has an impact on the development of atherosclerosis." (PMID 25240046, 2014). "Our study has confirmed the downregulation of Akt2 in F. nucleatum-infected macrophages, which may promote the disease progress such as periodontitis, colitis and atherosclerosis." (PMID 36513974, 2022). "Consistently, Rotllan and his colleagues found the same results and provided more evidence that Akt2 regulated cholesterol metabolism and targeting Akt2 in macrophages might be beneficial for atherosclerosis treatment." (PMID 30923552, 2019). "In contrast, a deleterious role for Akt2 in atherosclerosis has recently been elucidated." (PMID 25929188, 2015). "Macrophage Akt1 and Akt2 also have different effects on atherosclerosis." (PMID 25929188, 2015). "Macrophages express three Akt isoforms, Akt1, Akt2, and Akt3, but the roles of Akt1 and Akt2 in atherosclerosis in vivo remain unclear." (PMID 25240046, 2014). "The opposing effects of Akt1 and Akt2 in macrophage M1/M2 polarisation, inflammation and cholesterol accumulation indicate that Akt isoforms might have completely different or even opposing effects on atherosclerosis." (PMID 25929188, 2015). "It is possible that neutrophils may have contributed to the impact of Akt2 deficiency on atherosclerosis, but we did not see differences in the numbers of neutrophils in early lesions." (PMID 25240046, 2014). "However, the roles of macrophage expression of Akt1 and Akt2 in atherosclerosis remain unclear." (PMID 25240046, 2014).
diabetic nephropathy (7 papers, 2014 to 2025). "Research has also indicated that AKT2 has an important role in diabetic nephropathy via regulating antioxidant and apoptosis, which is consistent with our findings." (PMID 40986504, 2025). "Phosphorylation of Akt2 in the kidneys of STZ-induced diabetic rats: Increased expression of TGFβ with augmented signaling has been shown in the kidneys of patients with diabetic nephropathy." (PMID 30444896, 2018). "Based on the results of transcriptomics, the pathogenesis of diabetic kidney disease may involve 11 candidate differential genes: Egr1, Foxo3, Pik3r3, Fgf1, Sost, Wnt10a, Tgif2, Akt2, Mep1b, Col1a1, Apoe." (PMID 36249745, 2022). "Of note, the authors demonstrated a critical role of Fibroblast Growth Factor 21 (FGF21) in the protection conveyed by FF against diabetic nephropathy, as well as the activation of NRF2 through Akt2 signaling." (PMID 38474282, 2024).
metabolic syndrome (7 papers, 2008 to 2023). A cluster of metabolic risk factors for CARDIOVASCULAR DISEASES and TYPE 2 DIABETES MELLITUS. "Results indicated that two mutations, p.A179T and p.L183Q, may cause a reduction in AKT2 protein stability and functionality which can be a cause for IR, metabolic syndrome and T2D." (PMID 37754255, 2023).
cardiac hypertrophy (6 papers, 2013 to 2025). "Akt, particularly the Akt2 isoform, is integral to cellular signaling and has been associated with either promoting or inhibiting cardiac hypertrophy." (PMID 40144934, 2025). "Our salient findings revealed that ablation of Akt2 prolonged life span and rescued against aging‐associated contractile and intracellular Ca2+ defects, despite more pronounced ‘adaptive’ cardiac hypertrophy." (PMID 28681509, 2017). "Akt2, which is an activator of mTOR, is activated under HFD in the heart, and knocking out Akt2 prevented cardiac hypertrophy and preserved cardiac function by promoting maturation of autophagosomes in the heart." (PMID 34207151, 2021). "Perhaps the most intriguing finding from our study is that Akt2 ablation prolonged life span and rescued against aging‐induced cardiac dysfunction despite more pronounced cardiac hypertrophy." (PMID 28681509, 2017). "With the improved cardiac function in aging, the more pronounced cardiac hypertrophy in the face of Akt2 ablation seemed to suggest a state of adaptive cardiac hypertrophy in aged Akt2−/− hearts." (PMID 28681509, 2017). "As EF2 is a target for regulation of protein synthesis and AKT is known to be involved in cardiac hypertrophy, we examined the influence of several hypertrophic stimuli on AKT2/EF2-interaction." (PMID 23823123, 2013). "AKT2 ablation prolonged lifespan and improved cardiac aging through restored FOXO 1‐related autophagy and mitochondrial integrity, and chronic AKT activation accentuated aging‐induced cardiac hypertrophy and myocardial contractile dysfunction through a loss of autophagic regulation." (PMID 30168649, 2018). "Double knockout of cardiac Akt isoform (Akt2) and AMPK accentuated the HFD-induced increases in heart weight, cardiac hypertrophy, myocardial apoptosis, cardiomyocyte contractile, and oxidative stress." (PMID 37163421, 2023).
colitis (6 papers, 2019 to 2025). Inflammation of the colon. "This implies that colitis might be associated with the interaction of Akt1 and Akt2, which are important kinases mediating DSS-induced apoptosis." (PMID 36831001, 2023). "At in vivo level, in the colitis mice model, Akt kinase contributes to the polarization of macrophages and promotes M2 phenotype by deleting Akt2." (PMID 36513974, 2022). "As expected from these observations, Akt2-/- and WT mice transplanted with Akt2-/- macrophages were resistant to dextran sulfate sodium (DSS)-induced colitis." (PMID 36081513, 2022). "Mechanistically, our data showed that F. nucleatum aggravated dextran sodium sulfate (DSS)-induced colitis in the production of Th1-related cytokines IFN-γ through the AKT2 signaling pathway in vitro and in vivo." (PMID 31249571, 2019). "Additionally, allocryptopine improved the intestinal barrier and reduced the colitis response by inhibiting CX3CL1/GNB5/AKT2/NF-κB/apoptosis pathway." (PMID 37446938, 2023). "Our research may shed light on the mechanism by which ALL inhibits the CX3CL1/GNB5/AKT2/NF-κB/apoptosis pathway and improves the intestinal barrier to reduce colitis response and act on the CX3CL1–CX3CR1 axis to achieve neuroprotection." (PMID 36831001, 2023).
depression (6 papers, 2019 to 2023). "Akt has three subtypes (AKT1, AKT2, and Akt3), which play an important role in depression." (PMID 34479552, 2021). "There are three subtypes of AKT (AKT1, AKT2, and AKT3), and AKT1 is the most important subtype, which plays an important role in depression." (PMID 34257681, 2021). "Akt has three isoforms, AKT1, AKT2, and AKT3, which play an important role in depression." (PMID 36506595, 2022).
liver fibrosis (6 papers, 2019 to 2024). "Together, these results indicate that both Akt1 and Akt2 are involved in ethanol and LPS-mediated hepatic fibrosis." (PMID 31671832, 2019). "However, direct targets of AKT2 have been identified in other diseases like liver fibrosis and hepatocellular carcinoma." (PMID 36479211, 2022). "As the precursor of NAFLD, deleting AKT2, the downstream target of PTEN signal, can block the development of NASH and reduce the development of liver fibrosis, which also reduces the occurrence of NAFLD from another development process." (PMID 36866057, 2023). "Both STAT3 and AKT2 have been reported in the literature to be closely related to liver fibrosis, and inhibiting STAT3 or AKT2 can treat liver fibrosis." (PMID 35517817, 2022). "Furthermore, studies highlighting the mechanisms by which SREBP1c regulates hepatic stellate cells and liver fibrosis have revealed that the overexpression of SREBP1c inhibits liver fibrosis in mice by reducing TGF-β levels and signaling through SMAD3 and AKT1, AKT2, and AKT3." (PMID 38256181, 2024).
oral squamous cell carcinoma (6 papers, 2021 to 2024). "The upregulation of RAC-alpha serine/threonine-protein kinase (Akt1) and RAC-beta serine/threonine-protein kinase (Akt2) is the main cause of oral squamous cell carcinoma." (PMID 35251696, 2022). "For example, miR‐149‐3p reduces the viability and proliferative capacity of oral squamous cell carcinoma by decreasing AKT2 expression and increasing its sensitivity to the chemotherapeutic agent 5‐fluorouracil." (PMID 39162596, 2024). "Studies have shown that Clostridium nucleatum can promote the EMT in oral squamous cell carcinoma by regulating the lncRNA MIR4435-2HG\/miR-296-5p\/Akt2\/SNAI1 signaling pathway, thus enhancing cell migration." (PMID 36539710, 2022). "miR-149-3p inhibits cell proliferation by targeting AKT2 in oral squamous cell carcinoma." (PMID 35719192, 2022). "Oral squamous cell carcinoma is characterized by the upregulation of RAC-alpha serine/threonine-protein kinase (Akt1) and RAC-beta serine/threonine-protein kinase (Akt2)." (PMID 35251696, 2022). "In silico studies introduced LN as inhibitors of Akt1 and Akt2 with strong binding affinities of 11.5 kcal/mol and 11.1 kcal/mol, respectively, with no affinity toward MAOB, which can be an ideal candidate for oral squamous cell carcinoma treatment." (PMID 34832886, 2021). "Oral squamous cell carcinoma is characterized by overexpression of Akt1 (RAC-alpha serine/threonine-protein kinase) and Akt2 (RAC-beta serine/threonine-protein kinase)." (PMID 34832886, 2021). "It was reported that Akt1 and Akt2 inhibitors can lead to oral squamous cell carcinoma treatment with no affinity toward monoamine oxidase B (MAOB)." (PMID 34832886, 2021).